IL10 (interleukin 10)
Diseases named in the same sentence as IL10 in open-access papers (continued):
Sharing a sentence is not in itself a finding about the gene and the disease.
viral infection (continued). "Genetic factors also potentially influence IL-10 production in persistent viral infections." (PMID 31438973, 2019). "Prolonged IFN activation by persistent viral infection can produce an IL-10-predominant cytokine imbalance in the host, which contributes to T-cell exhaustion through induction of PD-1 expression, as shown in the lymphocytic choriomeningitis virus-infected mouse model." (PMID 31438973, 2019). "Thus IL-27’s impact on controlling viral infection seems to extend beyond its downstream mediator IL-10." (PMID 30044874, 2018). "HIV-infected CD4+ T cells can produce IL-10, leading to persistent viral infection." (PMID 29439673, 2018). "Importantly, our study also identifies that B cell-intrinsic IL-10 signaling is pivotal for sustaining humoral responses during chronic viral infection." (PMID 30487586, 2018). "Thus, our findings elucidate a critical role for Tfh-derived IL-10 in promoting humoral immunity during persistent viral infection." (PMID 30487586, 2018). "In this study, we further demonstrate that HCV-Exo-induced MDSCs contribute to an altered TFR/TFH cell ratio and IL-10/IFN-γ production, suggesting that chronic viral infection-caused premature immune aging recapitulates the nature aging process in the elderly." (PMID 30210805, 2018). "Co-infection did not blunt expression of typical antibacterial cytokines (il1b and tnfa); however, both type I IFN and the anti-inflammatory cytokine il10 were induced by the viral infection prior to bacterial superinfection, suggesting a contribution to the observed phenotype." (PMID 29881380, 2018). "IL-10 is produced by multiple cell types, including T cells, NK cells, monocytes, and B cells; NK cells are a major early source of this cytokine in response to viral infection." (PMID 29439673, 2018). "In addition to type I IFN, expression of the anti-inflammatory cytokine IL10 was induced by viral infection before bacterial superinfection." (PMID 29881380, 2018). "Thus our data reveals a “division of labor” for IL-10 and IFNγ in the resolution of inflammation following viral infection, with IL-10 being important for control of IMs and IFNγ being essential for termination of neutrophil responses." (PMID 29352287, 2018). "Notably the inhibitory role of IL-10 in suppressing T-cell responses during chronic viral infection is well-documented." (PMID 30487586, 2018). "As our results identified a critical role for IL-10-producing Tfh cells in supporting humoral immunity during chronic viral infection, we next sought to ascertain the inflammatory signals propagated during persistent LCMV infection that contribute to the formation of this protective cell subset." (PMID 30487586, 2018). "IL-10 effects in the course of viral infections depend on its spatial and temporal delivery." (PMID 28316998, 2017). "In addition to directly promoting virus reactivation, IL10 production by PCs has the potential to suppress humoral immunity and create a more permissive environment for viral infection." (PMID 28767707, 2017). "Finally, 10 days after viral infection, we observed more of the anti-inflammatory cytokine, IL-10, in the lungs of L. paracasei-fed mice compared to those gavaged with PBS." (PMID 28931041, 2017). "To explore whether direct virus infection induces the IFN-I production that would then drive IL-10 and PDL1 expression, we identified productively infected cells using an LCMV-Cl13 variant expressing GFP." (PMID 26808628, 2016). "IL-10 is also released by cytotoxic T cells to inhibit viral infection." (PMID 27072557, 2016). "IL-10 inhibition clears chronic viral infection in animal infection models." (PMID 27100390, 2016).
viral infection (continued). "However, while the expression levels of a large number of pro-inflammatory cytokines and chemokines were up-regulated, the mRNA levels of the antiviral genes IFN-α, IFN-β and the anti-inflammatory cytokine IL-10 were unchanged during viral infection." (PMID 28127293, 2016). "Whether attenuation of TST IL10 responses in this group of HIV-1 infected patients is due to decreased IL10 production by virus infected cells or indirect effects of virus infection on the immune system, requires further investigation." (PMID 26986567, 2016). "Furthermore, several studies show that during prolonged, highly inflammatory parasitic and viral infections, Th1 cells co-express the transcription factor Blimp-1, a transcriptional repressor that is required for Th1/Tr-1 production of IL-10." (PMID 27732671, 2016). "The timing of IL-10 expression and production by MØs during a virus infection could be a particularly important feature." (PMID 25430775, 2015). "When available, comparison of assays measuring IFN-γ, IL-10, and IL-6 may be useful for distinguishing between bacterial sepsis, viral infections, and HLH in febrile patients." (PMID 26347828, 2015). "However, certain members of Herpesviridae and Poxviridae transduced cellular IL-10 (cIL-10) genes at some point in their evolution and now express the viral IL-10 (vIL-10) orthologs in the context of viral infection." (PMID 25794555, 2015). "However, when IL-10 levels are already upregulated prior to viral infection such as in allergic asthma, the antiviral immune response is deficient, suggesting that the interaction between IL-10 and innate IFNs is not an “on-and-off” process." (PMID 25430775, 2015). "NK cells have been shown to produce IL-10 in response to viral infection." (PMID 24714634, 2014). "Moreover, it was reported that the induction of the regulatory IL-10 plays an important role to control the inflammatory process upon a viral infection to minimize tissue injury." (PMID 24886142, 2014). "Taken together, these in vivo results suggest that GCs and viral infection cooperatively increase IL-10 production, which may in part contribute to suppressing the host immune response against tissues and organs infected by MCMV." (PMID 23667643, 2013). "This release may prolong viral infection, and inhibiting IL-10 might facilitate the antiviral response." (PMID 23800014, 2013). "Infection with this virus was associated with increased expression of IFN-γ and IL-10 in the liver and decreased expression of IFN-γ and IL-18 in the spleen, providing useful information about important mediators involved in immunity against virus infection." (PMID 24204888, 2013). "We examined whether the cooperation of GC pre-treatment and viral infection on IL-10 expression could also be observed at animal levels." (PMID 23667643, 2013). "Indeed, DCs are major sources of circulating IL-10 secreted in response to viral infection, while they are also prime targets of this cytokine, being influenced in an autocrine or paracrine fashion." (PMID 23667643, 2013). "Furthermore, an experiment using IL-10 KO mice showed that IL-10 signaling plays a negative role in immunity against WNV infection and blockade of IL-10 signaling helps to control viral infection." (PMID 23940775, 2013). "During acute viral infections, IL-10 has paradoxical functions." (PMID 23012619, 2012). "Neutrophils have been shown to control lung pathology through the release of suppressor cytokines such as IL-10 and it is possible that this granulocyte subset contributes to host survival during virus infection by suppressing the cytokine storm induced in the lung in response to infection." (PMID 22615983, 2012). "In the context of viral infections, the presence of IL-10 may be considered either harmful or beneficial to the host." (PMID 22880122, 2012).
viral infection (continued). "IL-10 is a negative regulator of innate and adaptive immunity, and high levels of serum IL-10 may act as a feedback regulator of virus infection-induced inflammation." (PMID 22194944, 2011). "Recent evidence suggests that IL-10 may play an important regulatory role in acute viral infections of the respiratory tract where it inhibits the development of excess pulmonary injury in the face of normal virus clearance from the respiratory tract." (PMID 21829368, 2011). "In addition, IL-10 has been reported to suppress antiviral T-cell activity during persistent viral infection and Tat-induced IL-10 mediates immune suppression during HIV-1 infection." (PMID 20380696, 2010). "Interestingly, neutralization of IL-10 during persistent viral infection leads to recovery of virus-specific T cell responses and reduction of viral load, suggesting a potential therapy to restore T cell function and prevent viral persistence." (PMID 19816558, 2009). "In relation to viral infections, IL-10 may create favorable conditions for viral replication by disarming the innate and adaptive responses." (PMID 18000543, 2007). "Additionally, in specific viral infections, an overproduction of IL-10 might obstruct the elimination of pathogens and facilitate the advancement of the disease." (PMID 41601653, 2026). "However, little is currently known about how IL-10 activates STAT1 during viral infections." (PMID 40001503, 2025). "Moreover, the increase in IL‐21‐producing CD4+ T cells in participants with diabetes, which are important in providing B cell help and in enhancing the survival and function of cytotoxic CD8+ T cells upon vaccination or viral infection, was accompanied by a concomitant increase in IL‐10 production." (PMID 41367201, 2025). "Similarly, viral infection also induces the expression of several pro-inflammatory cytokines, including interleukin 6 (IL–6), interleukin 10 (IL–10), interferon β(IFN–β), and tumor necrosis factor α (TNF–α), all of which are significantly increased at the protein level." (PMID 39941149, 2025). "Although several hypotheses have proposed the pathogenic role of IL-10 in both viral infections, the occurrence of subsequent infections does not exacerbate cytokine production compared to SARS-CoV-2 infection alone." (PMID 39583156, 2024). "IL-10-mediated immunosuppression may play an important role in persistent viral infections." (PMID 36992486, 2023). "In summary, we have demonstrated that T-bet activity during a chronic viral infection can impede antiviral immune control by driving the development of highly differentiated TH1-like cells that express genes encoding inhibitory molecules, including IL-10 and Arg1." (PMID 37440306, 2023). "Both in the context of virus infection and cancer, sustained IFN-I signature is associated with chronic inflammation along with increases in immune checkpoint molecules, such as PD-1, PD-L1, IL-10 and IDO1 (indoleamine 2,3 dioxygenase 1), resulting in immunosuppression." (PMID 37686559, 2023). "The timing of IL-27 function during virus infection appears paradoxical, as early IL-27 signaling is important for enhancing innate antiviral responses and potentially regulating IFNγ production, but also may attenuate these very responses by increasing IL-10." (PMID 35634328, 2022). "In the acute phase, both IL‐6 and IL‐10 were increased in the patient group compared to the healthy people group, possibly because IL‐6 is an important factor in inducing B cells to differentiate into plasma cells to produce antibodies upon virus infection, and IL‐10 has an anti‐inflammatory effect." (PMID 33590892, 2021). "Notably, current pathological studies have shown that the severe patients infected by SARS-CoV-2 generally have higher plasma levels of IL-2, IL-6, IL-10, TNF-α, IFN-γ,41,43–45 implying a high risk of the inflammatory-associated cytokine storm after viral infection." (PMID 33895786, 2021).
viral infection (continued). "Viral infection could induce IL-10 production in macrophages." (PMID 32849638, 2020). "Notably, we have found that the estrous cycle is perturbed in IL-10 KO mice, indicating that the action of IL-10 on GnRH neurons might help the maintenance of the integrity of the estrous cycle in bacterial/viral infection." (PMID 31947687, 2020). "However, macrophages are also a major source of IL-10 production during viral infection." (PMID 32849638, 2020). "Thus we next performed comparative studies to determine whether acute or chronic viral infection differentially supports the formation of IL-10+IL-21+ co-producing Tfh cells." (PMID 30487586, 2018). "In this study, we set out to investigate whether IgA subclass production and B cell maturation are modulated by the T cell‐independent B cell class switch, survival and immunoglobulin inducing factors BAFF, APRIL, IL‐10 and RA in the context of bacterial or viral infection." (PMID 28921509, 2018). "Thus, therapeutic strategies aimed at enhancing Tfh production of IL-10 may serve to bolster humoral immunity during persistent viral infection." (PMID 30487586, 2018). "In line with our previous studies evaluating the effect of beneficial microbes on the susceptibility to viral infections, we found here that the respiratory commensal bacteria C. pseudodiphtheriticum improves resistance to RSV infection through the modulation of IFN-β, IFN-γ, and IL-10." (PMID 28878760, 2017). "Although virus-specific T cells were distributed throughout areas of the inflamed skin lacking overt virus-infection, IL-10+ cells closely associated with large keratinocytic foci of virus replication where they exhibited similar motility patterns to bulk antigen-specific CD8+ T cells." (PMID 26991092, 2016). "If the effects of these two risk factors for SIDS demonstrated in vitro reflect the responses to infection in vivo, the combined effects of cigarette smoke and virus infection on reduction of IL-10 could result in significant dysregulation of pro-inflammatory responses." (PMID 25814991, 2015). "Similarly, studies of antiviral states in macrophages have involved little attention on typical activation statuses, even though typical cytokines for macrophage polarization such as IFN-γ, IL-4, and IL-10 are rigorously regulated during monocytotropic viral infections." (PMID 26213635, 2015). "In addition to the involvement of extrinsic ADE-mediated viral infection, delayed viral clearance mediated through IL-10 immunosuppression may be involved in DENV pathogenesis." (PMID 23800014, 2013). "Based on our data we suggest that a higher production of IL10 following virus infection could be partially responsible for the worse outcome in males reported in murine models of HSV-1 infection or could be involved in the longer duration of viral lesions in human males." (PMID 22768144, 2012). "The upregulation expression of IL10 might skew the immune response away from a protective Th1-cell response towards a non-protective Th2-cell response, therefore impairing clearance of virus, which benefits viral infections." (PMID 20614006, 2010). "Other data to support the hypothesis that Th2-type responses increase susceptibility to virus infection include the observation that PBMC from Kenyan schistosomiasis patients with HIV-1 coinfection produce decreased levels of IL-4 and IL-10 compared to patients with schistosomiasis alone." (PMID 18648516, 2008). "Previous studies have identified monocytes and macrophages as primary sources of IL-6, IL-10, and TNF-α during viral infections, while IL-8 is typically secreted by macrophages and endothelial cells." (PMID 41522679, 2026). "Only no statistically significant slight enhancements were observed for IL1A, the anti-inflammatory IL10, and the interferon-gamma (IFNG) which increases during a viral infection and in some circumstances, it can act as a pro-inflammatory molecule." (PMID 41573543, 2025).
viral infection (continued). "ST3GAL2 resists viral infection by downregulating pro-inflammatory cytokines (IL-6, IL-18, IL-1β, IFN-β, TNF-α) and upregulating anti-inflammatory cytokines (IL-4, IL-10, IL-13)." (PMID 40755778, 2025). "Chronic viral infections, including CMV, can also enhance the production of immunosuppressive factors like IL-10, which lowers immune protection against Mtb and promotes Mtb persistence." (PMID 41050688, 2025). "Altogether, NK cell functions were suppressed by IL-10-producing Tregs in mice fed with HFD, suggesting an indirect detrimental effect of extensive lipid exposure on NK cell activity in a viral infection in vivo." (PMID 40352719, 2025). "While IL-10 is essential for preventing excessive tissue damage and maintaining immune homeostasis (e.g., respiratory syncytial virus), its elevated levels could result in immunosuppression during viral infections, enabling viruses to evade host defenses (e.g., foot-and-mouth disease virus)." (PMID 41156600, 2025). "In the late phase of acute viral infection, type II IFNs including IFN-γ and several other cytokines (including TNF-α and IL-10) are released by CD8+ T cells, strongly upregulating PD-L1 on various cell types." (PMID 38745748, 2024). "Borrelia-positive patients were distinct from viral infections in elevated CRP (Mann–Whitney two-sided, p = 0.030), IL-10 (p = 0.00038), and MIP-1Beta (p = 0.0048) and decreased IP-10 (p = 0.00028), IFN-alpha (p = 0.0022), and MCP-1 (p = 0.00038)." (PMID 38272885, 2024). "The loss of T cells has also been observed in various acute life-threatening viral infections, and the contribution of Fas/FasL and cytokines, such as TNFα, IL-6, IFN-γ, and IL-10, has been suspected." (PMID 38249467, 2023). "Higher levels of inflammatory mediators like IL-25, IL-1β, IL-10, IL-5 and tumor necrosis factor (TNF) -α after viral infection were found in human nasal epithelial cell (HNEC) culture compared to controls." (PMID 38116043, 2023). "We detected tissue-specific chemokine and cytokine storms in response to viral infection, including well-defined biomarkers in severe SARS-CoV-2 and IAV infections such as CXCL10, IL-6, and IL-10." (PMID 35962146, 2022). "In the course of viral infection, Th2 CD4+ T cells promote the humoral immune response by secreting IL-4, IL-5, IL-10 and other Th2 cytokines." (PMID 35100303, 2022). "There is increasing evidence that IL-27 is a potent inducer of IL-10 production from CD4+ and CD8+ T cells in a variety of viral infections, thereby having implications on antiviral immune responses and viral clearance." (PMID 35634328, 2022). "Significant reductions in IL-10-producing CD4+ and CD8+ T cells are observed during viral infection in il27ra-/- and ebi3-/- mice compared to their WT counterparts." (PMID 35634328, 2022). "During an acute virus infection, TFR-derived IL-10 is important for regulating Foxo1 activity and the capacity of GC B cells to down-regulate CXCR4 and cycle between the DZ and LZ of the GC." (PMID 33529242, 2021). "During chronic virus infection, mature populations of TFH cells served as a critical source of IL-10 to promote humoral immunity, although the specific mechanisms by which IL-10 programs either B cell fate or function were not formally explored in that report." (PMID 33529242, 2021). "The differential genes such as KITLG, FOXP3, miR-451, IL-2, IL-10, IL-6, and TNF-α are mainly involved in viral infection and the immune-inflammatory responses." (PMID 34867371, 2021). "The remaining 20 non-targetable SARS-CoV-associated disease genes include proteins (e.g., CD14, IFNA1, IFNB1, IL4, IL10, CCL5) having key roles in the immune-inflammatory response to viral infection as well." (PMID 33544720, 2021).